CIBAR2 (CBY1 interacting BAR domain containing 2)
Description:
May play a role in ciliogenesis (By similarity). In cooperation with CBY1 may facilitate ciliogenesis likely by the recruitment and fusion of endosomal vesicles at distal appendages during early stages of ciliogenesis.
Synonyms: FAM92B; FLJ44299
Gene: Protein-coding gene on chromosome 16 (85,098,358 to 85,112,472, reverse strand). Ensembl gene ENSG00000153789.
Subcellular location: Cytoplasm, cytoskeleton, microtubule organizing center, centrosome, centriole; Cytoplasm, cytoskeleton, cilium basal body
Genetic constraint (gnomAD): Loss-of-function variants: 30 observed, 29.28 expected, observed/expected ratio (o/e) 1.02, 90% interval 0.77 to 1.39. The upper end of that interval is the gene's LOEUF score, 1.39, which puts it in group 5 of 6, group 1 being the genes least tolerant of losing a copy. Missense variants: 395 observed, 324.8 expected, observed/expected ratio (o/e) 1.22, 90% interval 1.12 to 1.32. Synonymous variants: 151 observed, 127.22 expected, observed/expected ratio (o/e) 1.19, 90% interval 1.04 to 1.36.
Homologues: Orthologues: chimpanzee CIBAR2 (97% identical), macaque CIBAR2 (91% identical), dog CIBAR2 (71% identical), mouse Cibar2 (69% identical), pig CIBAR2 (65% identical), rat Cibar2 (64% identical), guinea pig CIBAR2 (61% identical), rabbit CIBAR2 (51% identical), tropical clawed frog cibar2 (48% identical), Drosophila melanogaster Fam92 (21% identical). Paralogues in human: CIBAR1 (39% identical).
Diseases named in the same sentence as CIBAR2 in open-access papers:
CIBAR2 is named in the same sentence as 6 diseases in open-access papers, as found by Europe PMC text mining. Sharing a sentence is not in itself a finding about the gene and the disease.
CIBAR2 shares sentences with these, for which no sentence is quoted: Alzheimer disease (1 paper); autism (1); cancer (1); Crohn disease (1); inflammatory bowel disease (1); metastatic tumors (1).